IL6 (interleukin 6)
Diseases named in the same sentence as IL6 in open-access papers (continued):
Sharing a sentence is not in itself a finding about the gene and the disease.
tumor (continued). "IL-6, in particular, is a powerful driver of Signal Transducer and Activator of Transcription 3 (STAT3) activation in both immune and tumor cells, supporting chronic inflammation, resistance to cell death, and the preservation of cancer stem cell traits." (PMID 40940809, 2025). "Studies have shown that the protumoral effects of M2 macrophages often coincide with PI3K/Akt activation, leading to increased IL-6 and TGF-β secretion, which in turn drives tumor cell resistance and enhances vascular permeability." (PMID 41002423, 2025). "After PD-1/Al@OV treatment, IL-1β and IL-6 levels were significantly reduced, while IFN-γ expression increased in tumor tissues, indicating that PD-1/Al@OV effectively enhanced the anti-tumor immune responses." (PMID 39955603, 2025). "Key cytokines of interest include IL-6, TNF-α, IL-1β (as prototypical pro-tumor inflammatory cytokines), as well as others such as IL-8 (CXCL8), IL-10, and IL-17, which together shape the tumor immune microenvironment." (PMID 41007766, 2025). "Targeting the NF-κB gene, IL-6 has been shown to markedly diminish the survival of GSCs in GBM, leading to a concurrent reduction in tumor growth." (PMID 40869207, 2025). "As already elaborated, tumor-cell-derived CCL3 activates the MAPK pathway, leading to the production of IL-1β, IL-6 and TNF-α." (PMID 41153795, 2025). "Elevated IL-6 levels also inhibited the production of CD8+ and CD4+ T lymphocyte cells, creating a “cold” tumor microenvironment (TME) that was unfavorable for anti-PD-1 therapy." (PMID 40160826, 2025). "Fibroblastic cells at the tumor invasion front have been shown to express RANKL and interleukin-6 (IL-6), both of which stimulate osteoclast differentiation and function, leading to progressive bone destruction." (PMID 40361486, 2025). "This polarization promotes the secretion of pro-inflammatory cytokines, such as interleukin-6 (IL-6), interleukin-8 (IL-8), and C-C motif chemokine ligand 2 (CCL2), thereby activating effective anti-tumor immunity." (PMID 39893499, 2025). "The bacterium can stimulate the NF-κB pathway, inducing the secretion of pro-inflammatory cytokines such as IL-6, IL-8, and TNF-α, thereby fostering a chronic inflammatory microenvironment that facilitates tumor initiation and progression." (PMID 41356485, 2025). "The activation of the PAM signaling pathway enhances the immunosuppressive functions of MDSCs, leading to increased secretion of inhibitory cytokines, such as IL-6 and TGF-β, which suppress the anti-tumor activity of effector immune cells." (PMID 40041495, 2025). "They prevent tumor growth through the secretion of pro-inflammatory cytokines known to inhibit tumor progression, including tumor necrosis factor-alpha (TNF-α), interleukin-1β (IL-1β), IL-6, IL-8, IL-12, and IL-23." (PMID 39857798, 2025). "IL-6 is a pivotal factor that drives the activation of the JAK/STAT3 signaling pathway, which is critical for promoting tumor angiogenesis and immune evasion." (PMID 41142809, 2025). "Interleukin-6 (IL-6) activates the JAK/STAT3 pathway, promoting tumor cell proliferation and immune suppression." (PMID 41311372, 2025). "Adipocyte-derived IL6 activates STAT3/NF-κB pathway in TNBC cells to promote the expression and secretion of CXCL1 in TNBC and promote tumor progression." (PMID 40841364, 2025). "The resected tumor mass from the G2 group showed an elevated IFN-γ level and reduced TNF-α and IL-6 levels; this finding suggested the infiltration of activated T cells into the tumor tissues." (PMID 40539041, 2025). "Both IL-6 and IL-8 can induce epithelial-to-mesenchymal transition (EMT), stimulate angiogenesis and tumor growth, and promote tumor cell migration in oral squamous cell carcinoma (OSCC)." (PMID 41479792, 2025). "THRs further impact the tumor microenvironment by regulating cytokines such as TNF-α and IL-6, contributing to immune evasion and cancer progression." (PMID 40926269, 2025).
tumor (continued). "IL-6 secreted by CAFs activates the Janus Kinases/Signal Transducer and Activator of Transcription 3 (JAK/STAT3) signaling pathway in tumor cells, thereby enhancing stemness, EMT, and resistance to apoptosis." (PMID 40940809, 2025). "BAT within the mediastinum secretes adipokines such as leptin and pro‐inflammatory cytokines (e.g., IL‐6, TNF‐α), which promote tumor cell proliferation, angiogenesis, and immune evasion." (PMID 40755324, 2025). "Similar results were obtained with cDC2s stimulated with IL-6 + M-CSF (+PGE2), tumor-derived cytokines known to be responsible for the conversion of cDC2s to CD14+ DC3s." (PMID 40789452, 2025). "IL6 and IL1B were significantly upregulated in tumor tissues compared with matched normal mucosa (p < 0.05)." (PMID 41267807, 2025). "Thus, peptides 1, 12 and 13 may reduce tumor spread and harm cancer cells by down-regulating IL-6." (PMID 40043049, 2025). "Several factors secreted by CAFs are involved in the regulation of M2 polarization, such as IL-4, IL-6, and TGF-β, thereby promoting tumor growth and metastasis." (PMID 40890855, 2025). "There were statistically significant differences in ECV, CRP, IL-6, NEU, and the status of other anti-tumor treatments between the two groups (P < 0.05)." (PMID 41199834, 2025). "Key cytokines such as interleukin-6 (IL-6), TGF-β, and IL-10, produced by immune and stromal cells within the tumor microenvironment, play a critical role in promoting tumor growth and creating an immunosuppressive niche." (PMID 40002248, 2025). "Concurrently, SASP reprograms cancer metabolism; IL-6-induced STAT3 activation shifts energy production toward glycolysis while suppressing oxidative phosphorylation (OXPHOS), thereby fueling rapid tumor growth." (PMID 40510156, 2025). "To examine MDSC-tumor interactions, we analyzed the GSE145374 dataset, identifying CSF2, SAA2, IL6, SAA1, and BCL2A1 as the top five upregulated differentially expressed genes in SKOV3 cells after co-culture with MDSCs." (PMID 41029721, 2025). "Inflammatory molecules such as IL-6, TNF-α, and IL-1β send signals that help tumor cells take in more glucose, produce more fats, and change how they use oxygen for energy." (PMID 41514860, 2025). "Treatment with trastuzumab induces repolarization of M2 to M1 macrophages, promoting an anti-tumor immune response through the release of pro-inflammatory cytokines such as tumor necrosis factor (TNF)-α and interleukin (IL)-6." (PMID 41400702, 2025). "SCs are able to secret multiple pro-tumor factors, such as IL-6, CXCL12, PGE2, etc. to participate in tumor progression." (PMID 40248695, 2025). "The IRE1α/XBP1 signaling also activates the IL6-JAK-STAT3 signaling and fatty acid metabolism in skeletal muscle of KPC tumor-bearing mice." (PMID 40655023, 2025). "Several cytokines are known to be involved in tumor development and immune modulation, including tumor necrosis factor (TNF)-α, IL-6, IL-10, IL-12, IL-17, transforming growth factor (TGF)-β, and macrophage migration inhibitory factor (MIF)." (PMID 41051525, 2025). "MDSCs take up extracellular vehicles released by tumor cells to activate cGAS–STING–NF‐κB signaling pathway and release IL‐6." (PMID 41427020, 2025). "A novel role of tumor-intrinsic PD-L1/JAK/STAT3/IL-6/MDSC axis in both immunosuppression and tumor progression has been recently reported in NSCLC." (PMID 40519900, 2025). "TAMs in ovarian cancer secrete cytokines like IL-6 and TGF-β, which promote tumor invasion and metastasis." (PMID 39911388, 2025). "This immunosuppressive axis is reinforced by PD-L1 upregulation: IL-6 and VEGF activate PD-L1 expression on tumor cells, impairing NK cell function and CD8+ T cell-mediated cytotoxicity." (PMID 40510156, 2025). "Curcumin is able to decrease levels of pro-inflammatory cytokines such as interleukin-6 (IL-6) and tumor necrosis factor-alpha (TNF-α) in order to control the tumor immune microenvironment." (PMID 40728996, 2025).
tumor (continued). "Autocrine IL-6 maintains MDSC survival through the STAT3-DNMT epigenetic axis, helping them evade necroptosis and accumulate in the tumor microenvironment." (PMID 41010517, 2025). "Curcumin inhibits tumor growth by reducing the levels of pro-inflammatory cytokines (e.g., TNF-α, IL-8, IL-6, and IL-1), also down-regulating the protein expressions of these cytokines." (PMID 40490812, 2025). "A significant correlation was found between tumor height and several cytokines, including β-NGF, CTACK, Eotaxin, IFN-γ, IL-16, IL-1α, IL-1ra, IL-6, IL-8, M-CSF, MCP-1, MIP-1α, and SCGF-β." (PMID 41048959, 2025). "With regards to altered immune regulation in tumor microenvironment, TAM-derived IL-6 promotes signal transducer and activator of transcription 3 (STAT3) phosphorylation, leading to decreased apoptosis in tumor cells." (PMID 39996747, 2025). "In CRC, ADAM17-mediated IL-6 trans-signalling and subsequent STAT3 activation drive tumour growth, as well as inflammation and immune evasion." (PMID 40427200, 2025). "IL6 also stimulates the p38 MAPK pathway in mesenchymal stem cells, enhancing adipogenesis and contributing to the tumor-supportive environment." (PMID 40427188, 2025). "For instance, curcumin inhibits NF-κB and COX-2 activation, decreases secretion of IL-6 and TNF-α, and downregulates inducible nitric oxide synthase (iNOS), thereby suppressing the pro-tumor inflammatory cascade." (PMID 41020838, 2025). "They secrete a range of cytokines and growth factors, such as IL-6, TGF-β, and VEGF, which contribute to tumor progression by promoting metastasis and invasion." (PMID 40443668, 2025). "Tumor HPV status, TMB, and interferon-γ-related signatures offer complementary prognostic information, whereas PI3K activation/IL-6 and myeloid-dominant TMEs flag potential resistance, supporting rational ICI combinations." (PMID 41374963, 2025). "CAFs also regulate immune suppression by recruiting immunosuppressive cells and inducing their polarization via cytokines such as IL-6, TGF-β, and Insulin-like Growth Factor Binding Protein 7, further blunting anti-tumor immunity." (PMID 40869364, 2025). "Experimental studies have demonstrated that surgical trauma activates pro-inflammatory cytokines (e.g., IL-6, TNF-α) and matrix metalloproteinases (MMPs), promoting tumor cell migration and invasion." (PMID 40236990, 2025). "CD4 + Th cells modulate the tumor microenvironment by secreting cytokines such as IFN-γ, TGF-β, IL-4, IL-5, and IL-6." (PMID 40441260, 2025). "This activation leads to an increased expression of various inflammatory cytokines within the tumor microenvironment, including TNF-α, IL-6, IL-1β, and other cytokines." (PMID 40487290, 2025). "Concurrently, Kupffer cells (KCs) secrete IL-6 and TGF-β, thereby inducing epithelial-mesenchymal transition (EMT) in tumor cells." (PMID 40823092, 2025). "IL6 is a known cytokine in the TME, affecting various crucial cellular components of the tumor immune microenvironment." (PMID 40227764, 2025). "Whereas IL-6/STAT3 promotes the Bcl-XL, Mcl-1, and VEGF, to inhibit apoptosis and promote cell survival by increasing angiogenesis and blood supply to the tumor." (PMID 40843259, 2025). "Tumor cells subvert neighboring B cells through IL-6/STAT3 signaling and CD40L-mediated activation, reprogramming them into pro-tumor effectors that secrete survival factors." (PMID 41246318, 2025). "Various cytokines produced by both tumor and stromal cells, such as GM-CSF, M-CSF, VEGF, IFN-γ, IL-4, IL-6, IL-13, and TGF-β, are involved in MDSC activation through STAT3 pathways." (PMID 40805183, 2025). "For instance, secreted circulating factors such as IL6, IL-1Ra, and CCL2 have been found to initially increase in patients after PD-1 pathway inhibition and correlate with tumor stabilization/shrinkage, as measured by objective response rates (ORR)." (PMID 39663510, 2025).
tumor (continued). "UMAP distribution showed that AKT1 and ESR1 were primarily expressed in tumor cells, SRC and IL6 were concentrated in the Myeloid subpopulation, while MTOR and HIF1A exhibited a broader distribution across multiple cell types." (PMID 40746726, 2025). "In dermal fibroblasts, TGF-β–induced CD70 enhanced NF-κB activation and secretion of IL-6 and MCP3, thereby reinforcing paracrine inflammatory loops that supported cSCC spheroid expansion and tumor progression." (PMID 41510255, 2025). "It was observed that both the Tumor B and Tumor groups exhibited reduced levels of GZMB and IFN-γ, indicating that IL-6 can diminish the effector killing capacity of CD8+ T cells." (PMID 40040705, 2025). "IL6 via the JAK/STAT3 pathway enhances the expression of hypoxia-inducible factor 1-alpha (HIF1α) under hypoxic and acidic conditions at tumor sites, leading to increased VEGF-A expression, which drives neovascularization and angiogenesis." (PMID 40427188, 2025). "In lung cancer, CAFs derived from freshly resected tissue have been shown to secrete immunosuppressive cytokines such as IL-6, TGF-β, and IL-10, which contribute to the immune suppression observed in the tumor microenvironment." (PMID 40453074, 2025). "M2 expresses high levels of CD163, CD206, CCL18, and CCL22, releasing anti-inflammatory (TGF-β, IL-4, and IL-13) and inflammatory (IL-6, IL-12, and TNF-α) factors, as well as tumor-promoting arginase-1 and VEGF, modulated by TME signals." (PMID 40940877, 2025). "Cytokines including, IL-6, and IL-1β engage in positive feedback interactions with CCL2 in the TME—a phenomenon with important implications for tumor therapy." (PMID 41341593, 2025). "Based on the published data, the high spontaneous secretion of IL-6 and IL-8 by cultured tumors of the luminal B HER2-positive subtype is likely the result of the activity of the cells that comprise the tumor, including its microenvironment." (PMID 40584290, 2025). "We examined the correlation between tumour Te‐EV m6A levels and TNF‐α and IL‐6 secretion by tumour Te‐EV‐treated dTHP‐1 cells." (PMID 40326665, 2025). "For example, TLR-4 activation leads to an increase in substances like interleukin-6 (IL-6) and tumor necrosis factor-alpha (TNF-alpha), which can help tumor growth." (PMID 40727443, 2025). "Upon activation by ω-3 LCPUFAs, PPARγ directly affects the NF-κB pathway and downregulates the level of pro-inflammatory factors such as MCP-1, IL-6, and TNF-α, so as to suppress neoplasia development." (PMID 39834867, 2025). "EAC tumor induction triggered a robust inflammatory response, significantly elevating plasma TNF-α (+ 104.1%), VEGF (+ 31.6%), and IL-6 (+ 169.4%) levels compared to normal controls (p < 0.05)." (PMID 41326498, 2025). "After tumour cells migrate to the endosteum, tumour cells stimulate the RANKL expression in osteoblasts through the production of PTHrP, prostaglandin E2, interleukin (IL)-6, IL-1β, enhancing osteoclastic bone resorption." (PMID 41027468, 2025). "In summary, low expression of AGPAT3 in tumor cells facilitated the accumulation of LPA, which promoted the IL-6 and IL-10 expression of TAMs through LAPR signaling." (PMID 41502512, 2025). "Antigen pulsing was performed by culturing the mDCs in the presence of cytokines rh-IL-4, rh-GMC-SF, rh-IL-6, rh-IL1b, rh-IL12, rh-IL-15, and rh-TNF-α and incubating 106 cells with 18 μg of tumor lysate or cultured cell lysate for 18 h." (PMID 40733726, 2025). "Along with IL-6, IL-8 is consistently overexpressed in TNBC and has emerged as a critical promoter of tumor progression, proliferation, EMT, migration, invasion (see Section 3), and angiogenesis (see Section 4)." (PMID 40868199, 2025). "Their results also indicated a significant increase in expression of IL6 and STAT3 in tumor biopsies." (PMID 40895532, 2025).
tumor (continued). "This change is accompanied by an upregulation of pro-inflammatory cytokines such as interleukin-6 (IL-6) and tumor necrosis factor-alpha (TNF-α), further enhancing the anti-tumor immune response." (PMID 40330466, 2025). "In breast cancer, HMGB1 enhances tumor stem cell self‐renewal capacity and promotes tumorigenesis and metastasis by activating TLR2, inducing IκBα phosphorylation, stimulating IL‐6 and TGF‐β secretion, and activating STAT3 and Smad3 signaling pathways." (PMID 41354099, 2025). "CAFs promote stem cell-like properties in malignant cells by activating the IL-6/STAT3/Notch axis, driving tumor aggressiveness and poor prognosis." (PMID 40755769, 2025). "Given that TNF-α signaling amplifies IL-6 and IL-8 secretion in the CRC TME, fostering apt conditions for tumor invasion, it is imperative to evaluate OC’s capacity to attenuate this cytokine axis." (PMID 40564985, 2025). "CAFs undergo tumor-driven reprogramming, secreting factors such as IL-6, ROS, and PDGF that promote tumor proliferation, invasion, and epithelial-to-mesenchymal transition (EMT), while remodeling the extracellular matrix to support malignancy." (PMID 41182416, 2025). "Intrinsic to the success of CAR therapy is the activation of the immune system via cytokines such as IL-1, IL-6, IL-10, TNF-a, and interferon (IFN)-g to kill tumor cells." (PMID 40264764, 2025). "Growth factors such as EGF, VEGF, FGF, IL‐10, IL‐6, TNF‐α, IFNγ produced by TAMs and NKs and miRNAs carried in tumour‐derived EVs promote tumour proliferation by activating pathways such as RAS–RAF–MEK–ERK–MAPK and PI3K–AKT–mTOR." (PMID 40525649, 2025). "This inhibition decreases the expression of key tumor-promoting factors like IL-6, VEGFα, MMP2, and MMP9, limiting the tumor-promoting environment created by TAMs." (PMID 40330466, 2025). "For instance, interleukin-6 (IL-6) and other inflammatory mediators in the TME enhance the immunosuppressive functions of MDSCs, leading to increased tumor growth and metastasis." (PMID 40872517, 2025). "In contrast, iCAFs secrete pro-inflammatory cytokines (e.g., IL-6, C-X-C motif chemokine ligand 12 (CXCL12)) to fuel tumor growth, while ApCAFs modulate adaptive immunity through antigen presentation, thereby shaping therapeutic responses in HCC." (PMID 41438763, 2025). "In PBMC humanized mouse model, combined blockade of IL-6 and PD1 enhanced the inhibition of tumor growth." (PMID 40040705, 2025). "They help sustain growth in hypoxic, nutrient-poor regions and are induced by paracrine cues (IL-6, TGF-β) and tumor exosomal miRNAs." (PMID 40940809, 2025). "Interactions between CAFs and tumor cells, mediated through TGF-β and IL-6 signaling pathways, reduce immune suppression and promote EMT." (PMID 41199747, 2025). "Inflammatory cytokines, such as interleukin-6 (IL-6), further exacerbate metastasis by activating the JAK/STAT3 signaling pathway, linking inflammation to tumor proliferation and dissemination." (PMID 40647432, 2025). "In contrast, iCAFs reside more distally from tumor cells, promote tumor progression, and exhibit low α-SMA expression while secreting high levels of IL-6, IL-11, and other pro-tumorigenic chemokines." (PMID 41156387, 2025). "CAFs are a key cell type in the TME and contribute to tumour progression through the secretion of ECM components (such as collagen and fibronectin) and protumourigenic factors (such as VEGF and IL-6)." (PMID 40861435, 2025). "EVs derived from GBM induce TAM secretion of CCL2, IL-6 and VEGF, which promote monocyte recruitment, tumor invasion, and angiogenesis, respectively." (PMID 40386422, 2025).